IL6 (interleukin 6)
Diseases named in the same sentence as IL6 in open-access papers (continued):
Sharing a sentence is not in itself a finding about the gene and the disease.
infection (continued). "CRP plays a key role in recognizing acute phase reactants released by infection, tissue damage, and inflammation mediated by the cytokine IL-6." (PMID 37114211, 2023). "Analyzing IL-6 following infection with Delta versus Omicron subvariants BA.5, BQ.1.1 and BF7 revealed a significantly higher cytokine secretion in Delta-infected cultures relative to UI or Omicron-infected cultures." (PMID 37915577, 2023). "Infection boosted IL-1β, IL6 and NLRP3 levels in TLR7 expressing AMФ but these proinflammatory markers were suppressed upon TLR7 deficiency." (PMID 37795093, 2023). "De plus, T. tenax a induit la production d'IL-6 à une faible multiplicité d'infection (MOI) dans les cellules de gencives, A549 et NCI-H292." (PMID 36971465, 2023). "This study showed that PbA-infected mice exhibited an increase in TNF-α, IL-1β, and IL-6 expression levels in the brain at day 13 post-infection." (PMID 37730604, 2023). "Our data demonstrated a significant reduction in the expression of IFN-α and IFN-β genes in IL-6−/− brains compared to WT brains at day 8 after infection." (PMID 38053527, 2023). "Our data demonstrated that the IL-6−/− mice had reduced levels of key cytokines in the serum during early infection but elevated levels of proinflammatory cytokines in the brain later, along with suppressed anti-inflammatory cytokines." (PMID 38053527, 2023). "Various cell types within the intestine, including macrophages, dendritic cells, T cells, and epithelial cells, produce IL-6 in response to diverse stimuli, such as infections, tissue damage, and inflammation." (PMID 37624306, 2023). "In earlier work, we found that blood-stage infection by the mutant self-resolved at day 12 post-infection (p.i.), displaying an immune signature that comprised elevated IL-6 levels, activation of T and B cells, and antigen-specific IgG2c production." (PMID 37143657, 2023). "As a cellular immune response to IAV infection, IL-6 is a pleiotropic cytokines produced in response to cell injury and infection." (PMID 37596622, 2023). "Using in vitro and in vivo infection models, we show that IL-6 induces phagocyte reactive oxygen species (ROS) that are responsible for the differential susceptibility of M4 and M1T1 GAS to IL-6-mediated defenses." (PMID 37874162, 2023). "The high peak at 120 days present in IL-6 dynamics shows that the infection induces IL-6 production, conversely to the vaccine." (PMID 37271819, 2023). "Higher levels of inflammatory cytokines such as IL‐8, IL‐6, and IL‐1β in bronchoalveolar lavage fluids (BALFs) have been associated with severe SARS‐CoV‐2 infection compared to moderate infection." (PMID 38099246, 2023). "As in the experiments above, our data shows that cells infected with exosome-free L. braziliensis produced significantly less IL-1β, TNF, IL-10 and IL-6 upon infection." (PMID 37841240, 2023). "We measured the viral titers in the serum and brains of WT and IL-6−/− mice at different time points following subcutaneous infection with WNV NY99 or JEV Nakayama strain by performing plaque assays." (PMID 38053527, 2023). "In mammals, alveolar macrophages exhibited polarization toward the M1 phenotype 4 h after H9N2 AIV infection, with the upregulation of M1-associated marker genes STAT1, TNF-α, MCP1, INOS, IL-6, and IL-12." (PMID 37357919, 2023). "Upon infection of the periodontal tissue by periodontal pathogens, macrophages produce proinflammatory cytokines like IL-1, IL-6, and TNF-α, which play crucial roles in regulating the inflammatory response to combat the infection." (PMID 37509571, 2023). "Coinciding with results of in vitro analyses, in vivo murine infection tests also proved that IL-6 was induced for a short period and rapidly diminished when the host was challenged with ΔrelAΔspoT mutant." (PMID 36937293, 2023). "At 24 h the IL-6 level was increased significantly by 193%, p < 0.0001 compared to 12 h post infection." (PMID 36707891, 2023).
infection (continued). "This in vivo IL-6 production correlates with the infection pattern of mice infected with IL-6 Tg-PbANKA/LISP2 SPZ, namely, a complete blockade of the parasite development at the liver stage." (PMID 37143657, 2023). "IL-4, IL-6, and IL-1 beta peaked by day 9 post-infection then dropped immediately prior to severe disease onset." (PMID 36992478, 2023). "Like IL-6 levels, we noticed a drastic increase in IL-17 level with increasing time points post infection." (PMID 36707891, 2023). "No immediate explanation was available for this as it is expected that the sex with higher infections would have higher pro-inflammatory cytokines such as IL-6 and lower anti-inflammatory cytokines such as IL-10." (PMID 37018184, 2023). "The expression level of IL-6 can also distinguish the severity of infection to some extent, as confirmed by previous findings." (PMID 37114211, 2023). "The transcription levels of the IL-6 gene in the brains of mice infected with both S. parasuis strains were slightly upregulated at 24 h post-infection and then gradually returned to the baseline level at 48 h post-infection." (PMID 37111486, 2023). "IL-6 is a critical mediator in infection and inflammation and one of the most studied biomarkers associated with cervical shortening in preterm labor." (PMID 37762154, 2023). "High IL-6 levels were observed during infection in both groups, although they were much higher in Group 2 (p = 0.046)." (PMID 36975498, 2023). "Intriguingly, we found that while cytokines related to acute viral response returned to normal levels upon infection clearance, the inflammatory response mediated by IL-6 and IL-18 remained elevated for weeks to months past infection resolution." (PMID 37490342, 2023). "S24, the expression of IL-6 was reduced by ~1.7 times under hybrid treatment, compared to the control groups, which suggests reduced infection promoting the wound recovery." (PMID 36696504, 2023). "High levels of IL-6 during catheterization were observed, which significantly increased during infection." (PMID 37790429, 2023). "IL-6 and KC levels peaked at 24 hrs and then gradually subsided, but remained elevated 17 days post-infection." (PMID 37724291, 2023). "It has been previously reported that LPS+IFN-γ primed Xiap−/− macrophages express reduced levels of IL-6 and TNFα upon infection with Listeria monocytogenes." (PMID 37347786, 2023). "In order to strengthen the results of pro-inflammatory cytokines, we used quantitative RT-PCR assay to test transcriptome levels of IL-6 and IL-8 in cells after infection." (PMID 36677452, 2023). "We observed relatively lower mRNA expression of inflammatory cytokines (IFN-γ, TNF-α, IL-4, IL-6, IL-17A and IL-33) in BA.5 infection as compared to ancestral Wuhan-Hu-1 infection." (PMID 37704701, 2023). "In the innate immune response, IL-6 is synthesised by myeloid cells, including macrophages and dendritic cells, at the site of infection or tissue damage after pathogens are recognized by Toll-like receptors (TLRs)." (PMID 37878647, 2023). "Fibrinogen, a positive acute-phase protein, produced in the liver on the stimulation of IL-6 and some other inflammatory markers, and its levels in plasma will increase with the presence of infection and inflammation." (PMID 37974066, 2023). "These modes are defined by the final viral load and IL-6 peak, to reflect the prolonged recovery of infection, and inflammatory status in patients." (PMID 37656752, 2023). "At day 1 after infection, the cytokine expression (IL-6, CXCL-9, IP10, and IFN-ß) in lung samples of MA60-treated, influenza virus-infected mice was stronger than in all other experimental groups." (PMID 38143489, 2023). "The pro-inflammatory cytokine IL-6 regulates antimicrobial responses that are broadly crucial in the defense against infection." (PMID 37874162, 2023).
infection (continued). "We can conclude that the in vitro pre-stimulus of cells with itaconic acid prior to infection with L. infantum increases the parasite load due to the overexpression of inflammatory markers such as Il6 and Cxcl9." (PMID 37235312, 2023). "The elevated IL-6 levels in the late infection stage suggest impaired pro-resolution functionality in humanized mice." (PMID 38035330, 2023). "The adjuvant group had a better effect in reducing TNF-α and IL-6 expression, which provided a basis for survival protection after infection in mice compared with the HA group." (PMID 37868069, 2023). "Two proinflammatory cytokines, MCP-1 and IL-6, were increased in wild-type rats following infection." (PMID 37366533, 2023). "Particularly, interleukin-6 (IL-6) plays a significant role in the human immune system’s response to infection and cell damage, and is secreted into the serum by T cells and macrophages in acute and chronic inflammation." (PMID 37754132, 2023). "Despite this decrease of inflammatory markers, at 72 h post-infection, a remarkable increase of cytokine expression (IL-17A, IL-6, IL-1β and IL-8) was detected." (PMID 37047702, 2023). "In our model, we ascribe Mode 1~3 with their increasing IL-6 level to patients experiencing more extensive infection and more severe symptoms." (PMID 37656752, 2023). "A drop in IL-6 was also evident at d3 post-infection in gp91-/- mice infected with A. nidulans, although the initial peak in IL-6 following A. nidulans infection was significantly lower than that seen in A. fumigatus infected mice (p<0.001)." (PMID 37724291, 2023). "CRP is a more sensitive inflammatory response protein produced by hepatocytes induced by IL-6, and its expression level increases when the body is exposed to trauma or infection." (PMID 36983320, 2023). "Significantly higher SARS-CoV-2 antigen-specific IgG, IFN-γ, IL-5, TNF-α, and IL-6 levels occurred in the breakthrough infection group compared to the booster immunization group (p = 0.013, 0.039, 0.024, 0.017, and 0.039, respectively)." (PMID 37515030, 2023). "Its production is induced by IL-6, and in a lesser proportion by IL-1 due to inflammation of infection." (PMID 36671362, 2023). "Key innate inflammatory cytokines, including TNFα, IL-6, IFNα, IL-10, IL-15, and IL-18, were all significantly elevated early during infection (days 1–5) compared to HCs." (PMID 36752598, 2023). "Blood indicators including ALT, AST, WBC, CRP and IL-6 indicated that both liver injury and systemic inflammation worsened as the infection progressed." (PMID 37587524, 2023). "We then infected these human cells with CoVs and measured the kinetics of IFN-β and IL-6 expression post-infection." (PMID 36507221, 2023). "However, the excessive amount of IL-6 may cause a cytokine storm during the anti-infection process." (PMID 38018195, 2023). "The secretion of TNF-α, IL-1β, and IL-6 can be up-regulated in response to infection with B. bronchiseptica, as these cytokines play a role in the immune response to the bacteria." (PMID 38066337, 2023). "CRP is an acute-phase reactant that is significantly elevated at the early stages of infection by mediation of inflammatory factors such as IL-6." (PMID 37362407, 2023). "Looking closer at the compound andrographolide, in in vivo experiments, this compound reduced the increase in TNF-α and IL-6 that followed infection of the lungs with S. aureus, while keeping them high enough to adequately manage the infection." (PMID 37765014, 2023). "In our study, the expression of the inflammatory cytokines IL-6 and IL-8 was highly upregulated in response to infection with the virulent RH strain." (PMID 37205102, 2023). "Chicks' immune systems are significantly activated by infection with Salmonella Enteritidis, resulting in an acute immunological emergency and excessive production of pro-inflammatory factors, including IL-1β, IL-6, and TNF-α." (PMID 37990191, 2023).
infection (continued). "In a similar manner, multiple bacterial-induced host proteins, including procalcitonin, C-reactive protein (CRP), and Interleukin-6, have been previously suggested to support the diagnosis of infection with limited precision." (PMID 37892652, 2023). "Pro-inflammatory cytokines, including tumor necrosis factor-alpha (TNF-α), interleukin-1 (IL-1), and interleukin-6 (IL-6), play crucial roles in initiating and amplifying the immune response by recruiting and activating immune cells at the site of infection." (PMID 37637609, 2023). "Leukocytes play a fundamental role in the healing of injuries due to the anti-infection action and immunological regulation through the secretion of immune cytokines, such as interleukin (IL)-1β, IL-4 and IL-6, and tumor necrosis factor alpha (TNF-α)." (PMID 37330965, 2023). "While IL-6 induced higher infection rates than resting CD4 + T cells alone, the addition of other cytokines did not induce additional infection." (PMID 37202790, 2023). "Following RV-A1 infection and apical compression, both inflammatory mediators (IL-6 and IL-8) at each time point were measured from apical PBS washes." (PMID 37280545, 2023). "At 24 h post infection, mice infected with the ΔrelAΔspoT mutant showed increased levels of IL-6 in both serum and lavage fluid samples in comparison with those infected with wildtype or complemented strain." (PMID 36937293, 2023). "As a major pro-inflammatory cytokine, IL-6 levels increase in patients with infection, as well as with trauma, surgery, and neoplastic infarction." (PMID 36383295, 2023). "A possible starting point for these findings is the involvement of the inflammatory cytokine IL-6, released by immune cells in response to infection or injury." (PMID 37932342, 2023). "Previous studies have shown that Acod1 and Il6 play an important role as immune regulators in maintaining homeostatic balance in the host and that the accumulation resulting from the infection response confers a powerful proinflammatory response to the host." (PMID 37643174, 2023). "The gp91-/- G-CSF and GM-CSF responses paralleled IL-6 and KC peaking at 24 hrs post-infection and subsequently resolving." (PMID 37724291, 2023). "In aged unvaccinated mice, although H7N7 infection increased IL-6 levels in the lungs compared to the Ctrl-PBS group (p = 0.005), vaccination successfully prevented this H7N7 IAV infection-induced increase (p = 0.02)." (PMID 37063291, 2023). "When compared to currently used biomarkers such as CRP, PCT, and IL-6, our methodology considerably reduces the time lag between the initiation of the infection and the response." (PMID 37932249, 2023). "In terms of the production of cytokines in synovial fluids, we observed that IL-6 was secreted at significant levels independently from the specific bacterium responsible for the infection, which is expected since IL-6 is used as a marker of infection." (PMID 37240374, 2023). "We observe both steady-state and infection-associated induction of pro-inflammatory and pro-fibrotic signaling in the former, including increased expression of TGFA, IL6, IL8, and IL20." (PMID 37874141, 2023). "In the case of IL12/23p40, the infection with S. Typhimurium also, as in the case of IL-6, significantly increased plasmatic IL-12/23p40 levels." (PMID 38003758, 2023). "At 24 h post-infection, S. suis strain P1/7 induced a significantly higher level of IL-6 production by BV2 cells than the two S. parasuis strains." (PMID 37111486, 2023). "Infection with NTHi is also associated with transcriptional upregulation of cytokines CCL2 (MCP1), TNF, IL-1β, IL-6, CXCL8 and alarmins (TSLP, IL-33 and IL-25)." (PMID 37180449, 2023). "BAL cytokines that were elevated peaked at mid-infection (42 days post inoculation) included, IL-6, IL-12, IFNγ, TNF, MIP-1β." (PMID 36893126, 2023).
infection (continued). "Under pathological circumstances, monocytes exhibit a reduced capacity to release inflammatory mediators like TNF, IL-1, IL-6, and IL-12 upon encountering severe infections." (PMID 37986183, 2023). "High levels of tumor necrosis factor (TNF), C-reactive protein (CRP), and interleukin 6 (IL-6) point to the involvement of infection and inflammation in the etiology of GDM." (PMID 36993820, 2023). "CXCL8 and IL-6 were also reported to increase in nasal aspirate after infection and show a strong correlation with symptoms." (PMID 36999069, 2023). "When IL-1β is released in response to infection or tissue damage, it activates other cytokines production, for instance, TNFα and IL-6." (PMID 38068877, 2023). "Pro-inflammatory cytokines (including IL-1β, IL-6, and IL-8) are necessary to initiate an inflammatory response during infection." (PMID 38026634, 2023). "Although these medications can quickly return the levels of infection-related biomarkers (e.g., IL-6 and CRP) to normal levels, patients treated with these drugs are at risk of virus recurrence (such as Patient # 4)." (PMID 37894092, 2023). "In the severe infection group, a machine learning model identified LCN2/NGAL, IL-6, and monocyte activation as parameters associated with fatality while anti-coagulant therapy was associated with survival." (PMID 37598150, 2023). "Pro-inflammatory cytokines (IL-6, IFNγ, TNFα, and IL-12p40) as well as the anti-inflammatory cytokine IL-13 increased, whereas release of IL-1Ra (an IL-1β inhibitor) was reduced by infection with the mutant strain." (PMID 37669276, 2023). "IL-6 can be persistently elevated in individuals with obesity and acutely following infection and exercise." (PMID 37312098, 2023). "In contrast, the IL-6 expression level was increased in human macrophages under hypoxia at 24 and 96 h post-infection and the PIAS3 expression level was increased at 24 h post-infection under normoxia." (PMID 36793725, 2023). "There are evidences that IL-10-dependent regulation of TNF, IL-6, and IL-1 reduces the inflammatory response, also reducing the probability of PB induced by infection and inflammation." (PMID 37340384, 2023). "It has been demonstrated that B cells in the lungs of I/St mice, which are sensitive to M. tuberculosis, release high levels of the proinflammatory cytokines IL-6 and IL-11 during infection by the H37Rv strain." (PMID 37686061, 2023). "Infection with ply+lytA+ strain A66 induced detectable IFNγ, IL-6, TNFα, RANTES, IL-1α and IL-1β in the lungs of inoculated mice, and all but IL-1α in the bloodstream." (PMID 36897919, 2023). "In comparison, in influenza (genus Influenza A/B/C/D) infection, the cytokines IL-1β, IL-4, IL-5, IL-6, IL-10, IL-12, IL-13, TNF-α, and IFN-γ are relevant to immune cell interaction in figures." (PMID 36851285, 2023). "Inflammatory factors like IL-6, IL-1β, and IFN-a or microorganisms biomarkers C. freundii, K. oxytoca, and E. cloacae need further research for indicating infection and constructing UTI diagnostic model of patients with CU." (PMID 36779185, 2023). "IL-6 and IL-17 are known to contribute to neutrophil chemotaxis during multiple infections/diseases (28, 31, –, 34)." (PMID 37338372, 2023). "It allows us to predict the probability that a patient will require hospitalization, intensive care, or mechanical ventilation, for which the blood IL-6 and IL-10 quotients during infection are calculated." (PMID 36979076, 2023). "This recognition can lead to a secretion of pro-inflammatory cytokines like IL-1β and IL-6 as well as chemokines that attract phagocytic heterophils and macrophages to the site of infection as a response." (PMID 37261344, 2023). "Overall we noticed a major increase in IL6 level at later time points post infection compared to initial time points." (PMID 36707891, 2023). "IL-6 is an important cytokine linking innate and acquired immunity and is essential for peripheral and central defense against impairment and infection." (PMID 38082215, 2023).